ERCC2 (ERCC excision repair 2, TFIIH core complex helicase subunit)
Diseases named in the same sentence as ERCC2 in open-access papers (continued):
Sharing a sentence is not in itself a finding about the gene and the disease.
tumor (81 papers, 2005 to 2025). "Mutations in ERCC2 cause it to lose its normal function, which makes tumor cells more vulnerable to substances that damage DNA, including cisplatin." (PMID 40736702, 2025). "XRCC1, XRCC3, ERCC1, and ERCC2 encode proteins crucial for the repair of DNA damage induced by ionizing radiation, directly affecting tumor cell radiosensitivity." (PMID 41463244, 2025). "DNA damage response and DNA repair pathways (for example, loss of function of ATM or ERCC2 mutation) are also affected; ERCC2 is involved in 24% of T1 tumours." (PMID 41008920, 2025). "Patients with ERCC2 mutations in pretreatment tumor biopsy specimens were more likely to achieve a complete pathologic response to neoadjuvant cisplatin than patients without ERCC2 mutations." (PMID 38675715, 2024). "For P4, persisting clones (clone A and C) served as source for newly arising clones with the acquisition of mutations (e.g., clone F with ERCC2 mutations) during tumor progression." (PMID 37176124, 2023). "Descriptive genomic analysis of pre-NAC tumor samples identified mutations in ERBB2 and DNA repair genes; ATM, RB1, FANCC, and ERCC2 were associated with tumor response to NAC." (PMID 33799514, 2021). "XPD has effects on progression of a broad palette of tumor types when mutated or altered—increased or decreased—in expression, and variants in ERCC2 have been associated with altered drug response, especially platinum-based therapies." (PMID 33733072, 2021). "Of these, we found that heterozygous missense mutations in four genes—FAT4, FAT1, FAT3, and ERCC2—were predicted to be deleterious and also detected by tumor RNA sequence data, indicating that the mutant alleles were expressed in the tumor." (PMID 33733072, 2021). "ERCC2 helicase domain mutations functionally impair NER pathway conferring cisplatin sensitivity to tumor cells." (PMID 33266377, 2020). "Several researchers have investigated the relationship between ERCC2 rs13181 and rs1799793 polymorphisms and chemotherapy efficacy in terms of tumour response and prognosis in gastric patients." (PMID 30581498, 2018). "Moreover, variations in the ERCC2 gene not only impact tumor susceptibility but also affect sensitivity to platinum-based chemotherapeutics." (PMID 40777111, 2025). "Third, additional studies on the effect of the ABCC2 rs2273697 and ERCC2 rs1799793 variants on protein expression in the tumor may contribute further evidence on the clinical utility of these variants as treatment predictors." (PMID 39771563, 2024). "Interestingly, the MSI-positive tumor also contained ERCC2 mutation with 50% prevalence of the altered allele." (PMID 37891989, 2023). "A previous report suggested tumor with ERCC2 functional deficiency was sensitive to cisplatin." (PMID 32984035, 2020). "Stratified analysis by tumor size feature demonstrated that ERCC2-rs13181 CA genotype carriers displayed an elevated risk of BC with large tumor size (T3-T4) in heterozygote model (OR: 4.09, 95% CI: 1.14–14.7, p = 0.03) and overdominant model (OR: 4.38, 95% CI: 1.28–15.1, p = 0.014)." (PMID 29544444, 2018). "We have also found that ERCC2-Lys751Gln polymorphism was related to tumor size." (PMID 24402573, 2014). "Polymorphisms in the ERCC2 gene may be associated with tumor susceptibility." (PMID 40777111, 2025). "The expression levels of the three genes of interest involved in the NER pathway (i.e., ERCC1, ERCC2, and ERCC5) were obtained from diagnostic FFPE tumor samples." (PMID 39735668, 2025). "There was an accelerated tumor growth and larger tumor weight in mice inoculated with ERCC2 overexpression-GL261 cells." (PMID 39768856, 2024). "Analysis of cBioPortal, the TCGA, and PanCancer Atlas database comprising 448 CM tumors found that ERCC2 is altered in 4% of the tumor samples (left)." (PMID 38028607, 2023).
tumor (continued). "RETAIN is a Phase II study that enrolls patients with MIBC to undergo surgery or a bladder-preserving approach according to the mutational profile of the tumor (including ATM, RB1, FANCC and ERCC2 mutations) (NCT02710734)." (PMID 33266377, 2020). "A previous study showed a tumor with a defect in the nucleotide excision repair gene ERCC2 was sensitive to platinum-based chemotherapy in MIBC and had a better prognosis." (PMID 32984035, 2020). "In this tumor, ERCC2 p.E606Q was identified, which is located in the DNA helicase domain and is conserved across species from human to zebrafish." (PMID 32984035, 2020). "Many single nucleotide polymorphisms have been identified in ERCC1 and ERCC2 genes; of these polymorphisms, ERCC1 (C118T & C8092A) and ERCC2 (A751C & G312A) have been shown to affect the repair capacity and concomitantly the tumor’s sensitivity to cisplatin." (PMID 29980176, 2018). "In regard to clinicopathological variables, our study showed that ERCC2-rs13181 heterozygote genotype was more prevalent in the BC patients with higher tumor size T3-T4 which is a poor prognostic indicator." (PMID 29544444, 2018). "Here, we detected an inverse correlation between miR-770-5p and ERCC2 expression both in tumor specimens from OVC patients who received platinum-based chemotherapy and in vitro." (PMID 27449101, 2016). "Like the seed microRNA and missense mutation SNPs in CYP1B1 that were strongly associated with tumor mutations in the present study, some of the identified RAD23B and ERCC2 SNPs also have potentially functional roles." (PMID 23637977, 2013). "In this small, yet novel, case-only study of genetic risk factors for GIST tumor subtypes we identified several variants in CYP1B1, RAD23B, GSTM1, and ERCC2 that we believe are worthy of further investigation." (PMID 23637977, 2013). "In two additional cases, germline A/G was replaced by G/G for ERCC2-312 (change of Asn/Asp into Asp/Asp in the tumor)." (PMID 20066159, 2009). "Somatic alterations in pre-specified genes (ATM, RB1, FANCC and ERCC2) or increased tumor mutational burden did not improve the positive predictive value of cCR." (PMID 37783966, 2023). "Tumor mutation burden (TMB) had weak positive correlations only with CD274 (p = 0.01342; R = 0.127), CXCL9 (p = 0.038; R = 0.1078), and also with the XP cluster 2 genes ERCC3 (p = 0.00196; R = 0.157) and ERCC2 (p = 0.027; R = 0.114)." (PMID 35174087, 2022). "Transcription factors like NOTCH1 (16%) and KMT2B (16%), UNC13C (14%), another tumor suppressor, ERCC2 (14%) involved in nucleotide excision repair pathway, were recurrently mutated, whereas genes like CDKN2A, MLH1, FGFR1, EGFR, etc. had a less than 10% mutation frequency." (PMID 34796107, 2021). "In conclusion, our results indicate that the ERCC1 rs3212986 and the ERCC2/XPD rs1799793 could be used as surrogate markers for a better stratification of EC patients with advanced resectable tumor." (PMID 30847299, 2019). "Furthermore, ERCC2 gene expression can be increased in tumor tissues." (PMID 39699591, 2025). "In a subset of retrospective clinical-genomic studies of MIBC, patients with somatic ERCC2 mutations were more likely to experience a pathologic complete response (pCR) following cisplatin-based neoadjuvant chemotherapy than patients lacking a tumor ERCC2 mutation." (PMID 40829180, 2025). "Interestingly, ERCC2 has also been implicated in a recent meta-analysis in higher tumor stage and grade, and a positive correlation with Ki-67 in HNSCC, suggesting a more aggressive tumor phenotype." (PMID 36552043, 2022).
tumor (continued). "However, urothelial cancer is unique in that it is the only known tumour type in which the core nucleotide excision repair (NER) gene ERCC2 is significantly mutated, whereas SBS5 activity has been identified in all tumour and normal tissues characterized to date." (PMID 35859169, 2022). "Therefore, the expression and function of DPYD, TYMS, MTHFR, ERCC1, ERCC2, XRCC1, and GSTP1 may be influenced not only by genetic polymorphisms, but also by processes that are specific for the tumor tissue." (PMID 33429840, 2021). "Moreover, ERCC2 expression levels may be used to distinguish between HBV-related HCC tumor and paracancerous tissues, which confirms its role in HBV-related liver damage." (PMID 33171788, 2020). "mRNA expression analysis and single nucleotide polymorphism (SNP) characterization of three NER pathway genes—namely ERCC1, ERCC2, and ERCC5—were performed on patient tumor samples." (PMID 39735668, 2025). "The higher gene expression of ERCC1, ERCC2, and ERCC5 in tumor samples compared to healthy control is consistent with previous studies that reported high tumor tissue levels of NER pathways genes, mainly ERCC1, in SCLC and in other solid tumors." (PMID 39735668, 2025). "Nevertheless, our germline analysis identified four genes with known functions likely to contribute to tumor progression and potentially drug response: FAT1 and FAT3, FAT4, and ERCC2, modeled by targeting kug, ft, and xpd, respectively." (PMID 33733072, 2021). "In this study, BRCA2 mutated tumors were, similar to ERCC2 mutated tumors, associated with high numbers of mutations in a SBS5 context, indicating that this mutational signature is an indicator of a DDR-deficient tumor that may be more sensitive to chemotherapy." (PMID 32978382, 2020). "Seven genes out of 13 (CCNH, ERCC2, ERCC6, NEIL1, OGG1, RPA1, XPA) had a significantly different expression in tumour versus normal tissue stored in PAXgene Tissue System." (PMID 27383461, 2016). "Regarding four commonly studied polymorphic sites in ERCC1, ERCC2/XPD, and XRCC1, it was interesting to identify discordant tumor tissue/peripheral blood genotypes." (PMID 20066159, 2009). "Our study demonstrated a significant increase in ERCC2 gene expression in tumor tissues, both in responders and non-responders, compared to normal control cells." (PMID 40736702, 2025). "In our study, changes in the rs13181 genotype of the ERCC2 gene were detected only in tumor tissue samples, but not in blood samples." (PMID 39699591, 2025). "This higher expression of ERCC2 in tumor cells is consistent with the findings of other investigators, who reported upregulation of ERCC2 in tumor tissue samples compared to noncancerous tissues." (PMID 40736702, 2025). "According to that, we hypothesized that miR-92a-3p triggers EMT in tumor cells through the activation of β-catenin, leading to the upregulation of DPYD, TYMS, MTHFR, ERCC1, ERCC2, and XRCC1 expression." (PMID 38659583, 2024). "We then investigated if a distinct genotype combination of ERCC1, ERCC2 and ERCC5 genes could influence the expression levels of these genes in the tumor tissue." (PMID 35955506, 2022). "This phenomenon may constitute an underexplored mechanism of chemoresistance in tumor cells under EMT, implying that expression of the genes DPYD, TYMS, MTHFR, ERCC1, ERCC2, XRCC1, and GSTP1 may be modulated EMT-TFs." (PMID 33429840, 2021). "ERCC1 and ERCC2 (XPD) have pivotal roles in the NER pathway, this has been evidenced in studies where lower levels of intratumoral ERCC1 mRNA are significantly correlated with improved survival due to enhanced tumor cell sensitivity to cisplatin." (PMID 25452763, 2014). "In another case, germline ERCC2-312 Asp/Asp (no amplification of the Asn target) was replaced by Asn/Asp (dCt = 1.1) in the matched tumor tissue." (PMID 20066159, 2009).
tumor (continued). "However, gender, primary tumour location, and the XRCC1-rs25487, ERCC1-rs11615, ERCC2-rs238406, and ERCC2-rs13181 polymorphisms were not statistically associated with 5-year OS (p’s > 0.05)." (PMID 32397974, 2020). "ERCC2 G-C haplotype was correlated with PR negative and larger tumor (T4)." (PMID 29544444, 2018). "For rs13181 of the ERCC2 gene, the differences were observed only for genotypes and OC tissue samples: a statistically significant decrease in OR was found in heterozygotes T/G for tumor tissue samples, and it was not statistically significant in blood samples." (PMID 39699591, 2025). "In 2/10 unmatched tumor tissue samples, allelotyping data could be obtained for ERCC1 but not for ERCC2 and XRCC1, probably due to poor FFPE DNA quality." (PMID 20066159, 2009).
genetic diseases (7 papers, 2007 to 2025). "Mutations in ERCC2/XPD are linked to multiple human genetic disorders that were initially defined as DNA repair syndromes." (PMID 36065184, 2022). "Mutations in ERCC2/XPD helicase, an important component of the TFIIH complex, cause distinct human genetic disorders which exhibit various pathological features." (PMID 36065184, 2022).
adenocarcinoma (3 papers, 2007 to 2021). A common cancer characterized by the presence of malignant glandular cells. "A range of ERCC2 protein expression was observed, from low or undetectable to strongly positive in adenocarcinomas from CRC patients." (PMID 33809839, 2021).
infection (3 papers, 2009 to 2024). The state of being infected such as from the introduction of a foreign agent such as serum, vaccine, antigenic substance or organism. "Unfortunately, when IVIG therapy was stopped in one patient the patient died from severe infection thus highlighting the importance of immunological investigation and subsequent treatment in patients with ERCC2 deficiency." (PMID 39055713, 2024). "in 2008 revealed that ERCC2 mutations represented the most common genetic defect in TTD patients and were present in almost half of the patients who presented with recurrent and/or severe infection." (PMID 39055713, 2024).
autosomal recessive disease (2 papers, 2015 to 2022). Autosomal recessive form of disease. "Among ERCC2/XPD-related disorders, CS is a rare autosomal recessive disease that presents with multiple organ degeneration and premature aging." (PMID 36065184, 2022).
gynecological tumors (2 papers, 2025). "Numerous studies have investigated the relationship between ERCC2 gene polymorphisms and gynecological tumors; however, their findings remain controversial." (PMID 40777111, 2025). "In this paper, we summarized a larger sample for meta-analysis to explored the relationship between the polymorphisms of the ERCC2 Lys751Gln, Asp312Asn, and Arg156Arg and gynecological tumors." (PMID 40777111, 2025). "The ERCC2 Lys751Gln polymorphism was found to increase the risk of gynecologic neoplasms(C vs A:OR 1.33, 95% CI 1.06-1.66;CC+CA vs AA:OR 1.33, 95% CI 1.11-1.59)." (PMID 40777111, 2025). "The results of meta-analysis of the association between ERCC2 Asp312Asn polymorphisms and gynecological tumors were as follows." (PMID 40777111, 2025). "However, several studies have investigated the association between ERCC2 polymorphisms and the risk of gynecological tumors, but the results have been inconsistent." (PMID 40777111, 2025). "However, the relationship between ERCC2 gene polymorphisms and susceptibility to gynecological tumors remains unclear." (PMID 40777111, 2025).
bacterial infection (1 paper, 2020). "Functional annotation of putatively selected genes revealed that these genes were predominantly associated with immune-related functions, inclusive of genes such as C5AR1 and MYH10 (bacterial infection); ARHGEF1, ERCC2 and TRAF2 (viral infection) and IFNGR2 (both viral and bacterial infection)." (PMID 33116287, 2020).
peripheral neuropathy (1 paper, 2013). A disorder affecting the peripheral nervous system. "In the present study, correlations were identified between the polymorphism patterns of TS, MTHFR, ERCC1, ERCC2, GSTP1, GSTT1 and GSTM1 and the clinical outcome, including the incidence of peripheral neuropathy, in Japanese MCRC patients who were treated with modified FOLFOX6 (mFOLFOX6)." (PMID 24137384, 2013).
ERCC2 also shares sentences with these, for which no sentence is quoted: non-small cell lung carcinoma (7 papers); acute lymphoblastic leukemia (3); breast (3); acute leukemia (2); DNA repair deficiency (2); Fanconi anemia (2); glaucoma (2); head and neck tumor (2); leukemia (2); neuroblastoma (2); non-Hodgkin lymphoma (2); non-melanoma skin carcinoma (2); preeclampsia (2); testicular cancer (2); Urothelial Bladder Cancer (2); Xeroderma pigmentosum complementation group C (2); acute coronary syndrome (1); acute myeloid leukemia (1); adenocarcinoma of the pancreas (1); adenomyosis (1); Age-related cataract (1); asthma (1); astrocytic tumor (1); basal cell carcinoma (1); beta thalassemia (1); breast tumor (1); carcinoma in situ (1); cardia gastric cancer (1); cardiovascular disease (1); cerebrooculofacioskeletal syndrome 2 (1).
A further 67 diseases each share a sentence with ERCC2 in 1 paper.